RNU6-210P (RNA, U6 small nuclear 210, pseudogene)
Gene: Small nuclear RNA gene on chromosome 1 (93,010,257 to 93,010,351, forward strand). Ensembl gene ENSG00000252752.
Homologues: Orthologues: chimpanzee U6 (99% identical), macaque U6 (95% identical), guinea pig U6 (71% identical), dog U6 (63% identical), guinea pig U6 (61% identical), rabbit U6 (61% identical), guinea pig U6 (60% identical), mouse Gm26403 (56% identical). Paralogues in human: RNU6-38P (84% identical), RNU6-477P (84% identical), RNU6-1145P (83% identical), RNU6-1011P (81% identical), RNU6-1316P (81% identical), RNU6-15P (81% identical), RNU6-20P (81% identical), RNU6-224P (81% identical), RNU6-25P (81% identical), RNU6-29P (81% identical), RNU6-41P (81% identical), RNU6-47P (81% identical), and 1287 more.